IL10 (interleukin 10)
Diseases named in the same sentence as IL10 in open-access papers (continued):
Sharing a sentence is not in itself a finding about the gene and the disease.
infection (continued). "In mice infected with S. aureus, MDSCs inhibited monocyte/macrophage-mediated anti-bacterial immunity by producing high levels of IL-10, thus leading to infection persistence." (PMID 32931721, 2020). "IL-10 was reported to contribute to the pathology observed following infection with this strain of L. major." (PMID 33212818, 2020). "In a previous study, we demonstrated that H. pylori infection in vivo induces strong regulatory mechanisms driven by IL-10-expressing myeloid cells starting at day 14 post infection and reaching maximum levels at day 28 post infection." (PMID 32661418, 2020). "We found IL-27 signalling was critical for the development of IL-10-producing Th1 (Tr1) cells during infection." (PMID 33049000, 2020). "The study uncovered a complex process where IFN-γ producing Th1 cells secrete IL-10 in the early stages of infection and counteract NA-mediated activation of latent TGF-β in flu-specific CD4+ T cells." (PMID 32974217, 2020). "In contrast, infection of Unc93b13d/3d mice resulted in significant but reduced IL-10 levels compared to WT mice." (PMID 32634175, 2020). "The anti-inflammatory role of Tregs has been confirmed in experimental infections with Trichinella spiralis, where suppression of gut inflammation was related to the increased expression of IL-10 and TGF-β and expansion of Tregs." (PMID 32268573, 2020). "The dysregulation in the chronic activation leading to exacerbated cytotoxicity points to the mandatory requirement of IL-10 to fine-tune the immune response during an infection." (PMID 32210950, 2020). "Cytokines decreased sharply at 8 weeks post-infection, while the levels of IL-10 and IL-21 increased significantly." (PMID 33330140, 2020). "The mRNA for regulatory cytokine Il10 increased after infection, with the highest levels in the brains of WT-infected mice at 6 days (P < 0.0001) and in spinal cords at 4 days (P < 0.0001)." (PMID 32047134, 2020). "Interleukin-10 expression peaked three days post-infection in vitro, while others have reported that in vivo, murine serum IL-10 peaked on day five post-infection during MCMV infections." (PMID 32455939, 2020). "Both brain mRNA levels and cytokine concentrations of IL-4 and IL-10 were shown to be upregulated after infection with A. cantonensis, whereas those of IL-2 and IFN-γdecreased." (PMID 32635653, 2020). "On the contrary, infection with both strains resulted in a reduction in the IL-10 gene expression at later time pi." (PMID 32178332, 2020). "This phenotype coincides with increased systemic levels of IL-10 during the later stages of infection." (PMID 32012211, 2020). "They suggested that the strong association between P. knowlesi parasitaemia and neutrophils involved the cytokines IL-1ra and IL-10, which were related to anti-inflammatory effects on the patient’s response to infection." (PMID 32727617, 2020). "When analyzing IL-10 in serum samples, it was observed that infection with the parasite increased IL-10 levels systemically (p = 0.0262), and mice infected and treated with DFO or FeSO4 apparently produced more IL-10 compared with non-infected mice." (PMID 32295126, 2020). "The levels of inflammatory cytokines decreased sharply at about 8 weeks post-infection, at which time the levels of IL-10 and IL-21 peaked." (PMID 33330140, 2020). "The levels of IFN-γ, IL-12, and IL-6 in mouse serum peaked at 6 weeks post-infection, and IL-10 and IL-21 levels peaked at 8 weeks post-infection." (PMID 33330140, 2020). "In contrast, reports have highlighted IL-10 to have different roles in infection models of the lymphocytic choriomeningitis virus, Schistosoma mansoni, Mycobacterium tuberculosis and Candida albicans where it impedes control and clearance of these pathogens." (PMID 32684836, 2020).
infection (continued). "This is associated with a discreet increase in IL-10, an anti-inflammatory cytokine, probably due to a lower level of the production of LTB4, even in the presence of an infection with Aggregatibacter actinomycetemcomitans." (PMID 32764374, 2020). "In L. donovani infected C57BL/6 mice, the frequency of splenic IFN-γ+ IL-10+ T-bet+ CD4+ T cells is increased on day 28 post-infection." (PMID 32849534, 2020). "Our results indicate that COX-2 up-regulation benefits host defense against ExPEC XM O2:K1:H7 infection by increasing autophagy in macrophages and by reducing IL-10 expression and macrophage cell death during ExPEC infection." (PMID 32362888, 2020). "In contrast, IL-1β, IFN-γ, IL-22, IL-10, IL-27 and IL-35 were present in lower levels in the lungs of these mice at all post-infection periods assessed." (PMID 32647342, 2020). "In contrast, the induction of IL-10 in local tissues during early infection was observed in the present study." (PMID 32404209, 2020). "After 4 weeks of infection, the host's immune response shifts to a Th2 type, producing cytokines such as IL-4, IL-10, and IL-13." (PMID 32373112, 2020). "Using IL10−/− mice, we find that infection with E. coli NC101, ETBF, or Helicobacter species, or tissue damage caused by dextran sodium sulfate (DSS) leads to inflammation, which generates an accumulation of oxidative DNA damage in colonic tissue." (PMID 32286276, 2020). "The raised levels of IL-6 (632 ± 526Vs 17 ± 8 pg/ml, day 15 post-infection) and IL-10 (88 ± 60 vs. 30 ± 27.41 pg/ml, day 12 post-infection) were quantified in the mice infected with C9-M parasites and compared with NF54 wild type P. falciparum." (PMID 33013831, 2020). "In mice, MCMV relies on IL-10 expression upon infection to repress the mouse immune system and facilitate persistent infections in vivo." (PMID 32455939, 2020). "B10 cells, a Breg subset, have been shown to limit immune response to pathogen infection via the release of interleukin-10 (IL-10)." (PMID 32257991, 2020). "Taken together, these results demonstrate that H5N1 (2:6) infection results in higher expression of inhibitory signals such as PD-1 and IL-10 by T cells, which likely suppress cytotoxic T cell functions in vivo." (PMID 32075925, 2020). "Infection of wildtype mice with L. monocytogenes results in high levels of serum IL-10 3–4 days post infection." (PMID 32634175, 2020). "This was in contrast to the immunosuppressive infection of macrophages with live parasites, marked by IL10 production." (PMID 33051524, 2020). "Interleukin (IL)-10 has been shown to be the master regulator of immunity, infection and immunodepression." (PMID 32106601, 2020). "Following clinical recovery from infection, IL-10 levels returned towards that of healthy volunteers." (PMID 32699255, 2020). "In humans, high levels of IL-10 have been associated with severe disease, however this is often attributed to IL-10 mediated immune suppression impairing the ability of the patient to control the infection." (PMID 32974217, 2020). "In the liver, on the first day after infection, an upregulation of IFN-γ and IL-10 expressions was observed in susceptible C57BL/10 mice when compared with C3H/He mice (respectively)." (PMID 32983013, 2020). "Alternatively, a study of IL-10 knockout mice observed increases in the Th17 response were protective against high-dose infection." (PMID 32974217, 2020). "The infection of mice with influenza virus has been shown to trigger increased IL-10 levels in reconvalescent animals, but ultimately resulted in an increased susceptibility to S. pneumoniae infection and a lethality of 100%." (PMID 31947746, 2020). "The anti-inflammatory cytokine IL-10 was up-regulated in the cerebellum of the infected animals and progressively increased from day one, raising its peak on day 60 post-infection." (PMID 33322180, 2020).
infection (continued). "TLR4-deficient IL10-/- mice, however, displayed less severe clinical signs of infection, that were accompanied by less distinct apoptotic epithelial cell and innate as well as adaptive immune cell responses in the colon, as compared to IL10-/- counterparts." (PMID 32443576, 2020). "On day 5 post-infection, both oral administration of valine and intraperitoneal injection of CoA can significantly reduce virus titers and levels of IL-1β, IL-6, and IL-10 of the lungs and at the same time upregulate IFN-β and IFN-γ of the lungs." (PMID 32345342, 2020). "After 8 days post infection, Il10−/− mice infected with Cj-P1 demonstrated severe morbidity and bloody diarrhea and the experiment had to be terminated." (PMID 33257743, 2020). "At all post-infection times assayed, a reduced presence of Treg cells was here observed in line with reduced Foxp3 mRNA detected and the low levels of IL-10, TGF-β and IL-35, cytokines involved in the suppressive activity of this T cell subpopulation." (PMID 32647342, 2020). "IL-8 is a potent chemoattractant and stimulator of neutrophil accumulation in the respiratory system upon infection while IL-10 serves to inhibit inflammation, thus reducing the damaging effect of the tissues due to inflammation." (PMID 33585281, 2020). "Our study found that Ms_Rv0341 infection significantly induced the expression of IL-10 compared with the control strain." (PMID 32521796, 2020). "Altogether, these results showed that L. amazonensis infection causes an impairment in the immune response in the spleen of C57BL/10 mice during all infection, with higher upregulation of IL-10, mainly at later times where the parasite load is high." (PMID 32983013, 2020). "In contrast, early production of excessive IL-10 and IL-13 antiinflammatory cytokines observed in the serum of WT mouse after 2 wk of infection promoted Mtb growth." (PMID 32139610, 2020). "After co-treatment with Alb and Sch B, IL-10 levels were found to be decreased compared with those in the infection group." (PMID 32635653, 2020). "IL-10 expression was upregulated (1.3 ± 0.15) prior to infection, and (1.1 ± 0.15) in post-infection compared to untreated infected cells (0.51 ± 0.3) (p < 0.05)." (PMID 32635645, 2020). "In pregnant women, it was observed that high levels of IL-10 was a good predictor of infection and maternal anemia." (PMID 33281757, 2020). "Previous in vivo studies following experimental infection with Ab4-wt (neuropathogenic) strain showed release of fewer cytokines/chemokines at low concentration (IL-10, CCL2, CCL3) in comparison to RacL11 and NY03 strains (abortigenic strains)." (PMID 32911663, 2020). "The serum level of IL-10 increased in klotho WT and KO mice after infection and was significantly higher in klotho KO mice than in klotho WT mice at 1 day post-infection." (PMID 33329595, 2020). "It was found that pre-exposure of B. malayi microfilariae decreased the expression of IL-10, IFNα, and macrophage inflammatory protein-1β by DCs and the expression of IL-10 and IFNα by macrophages after infection with M. tuberculosis." (PMID 33193291, 2020). "In group 3, down regulation of IL-22 and IL-10 was seen in spleen at pre-adult stage of infection (28 dpi), which in turn is related to the increase observed in pro-inflammatory cytokines at adult stage (50 dpi)." (PMID 33006991, 2020). "Interleukin-10 (IL-10) is a master regulator of immunodepression, but it is still not clear if systemic IL-10 levels contribute to immunodepression, occurrence of infections and clinical outcome after SAH." (PMID 32106601, 2020). "In a previous report, specific pathogen free (SPF) chickens inoculated with a high-virulence C. psittaci strain were determined to have high IL-10 and IL-6 expressions, which resulted in immune suppression and secondary infection of H9N2." (PMID 32183481, 2020).
infection (continued). "UC patients with inactive and mild endoscopic and histological activity and HP-negative infection showed some increased levels of IL-10 compared with HP-positive (P < 0.05)." (PMID 32695157, 2020). "At 14 days post infection (directly after treatment) very high concentrations of IL-2, IL-13, IL-10, IFNγ, IL-6, and TNFα were observed." (PMID 32226027, 2020). "When patients were grouped by the presence of persistent bacteraemia, we observed higher IL‐17, IL‐10 or sE‐selection in patients with endovascular foci (IE and non‐IE) than extravascular infections only in the non‐persistent group." (PMID 32082571, 2020). "IL-10 was significantly induced 6 h after the bacterial infection and its level was sustained up to 12 h after the infection." (PMID 32153580, 2020). "Here, we identified the peptidase PepP by casein zymography and mass spectrometry, and demonstrate that inactivation of its gene in C. jejuni strain 81–176 resulted in a marked decrease of virulence during infection of microbiota-depleted IL-10−/- mice." (PMID 32584649, 2020). "For example, IL-6 as a lymphocyte stimulating factor was first produced to induce innate and adaptive immune responses in the early infection, but IL-10 is a regulator to alleviate hyper-inflammation for prevention tissues damage in the late infection." (PMID 33044969, 2020). "After secondary infection, transcript production for iNOS, IL-6, and IL-10 was increased while Il4 was strongly reduced in sham and CLP-operated mice." (PMID 32425929, 2020). "IL-10 and TGF-β4 have anti-inflammatory properties, and their increased level in pathogen-infected hosts is associated with increased susceptibility to infection." (PMID 32054193, 2020). "In this study, the combined hormones induced the gene expression of the anti-inflammatory cytokine IL-10 (~twofold), which was maintained as up-regulated upon infection." (PMID 32605209, 2020). "Elevated levels of IL-10 have also been reported in these infections and multiple studies have reported a direct link between loss of cytotoxicity and increased levels of IL-10." (PMID 32210950, 2020). "Once the infection progresses to disease, patients present a predominance of anti-inflammatory mediators, such as IL-10, which can encourage parasite multiplication and interfere with infection control." (PMID 32210480, 2020). "The production of IL-10 increased slightly in WT PE-Mφ only with infection or with infection + IFN-γ." (PMID 31906385, 2020). "A gradual decrease in the absolute number of B cells (per mL blood) was observed in all groups of mice, yet TgAlbCre-IL10-/- mice exhibited significantly lower numbers of B cells between day 38–48 post infection compared to WT and LysM-IL-10-/- mice." (PMID 32012211, 2020). "In IL-10 deficient mice infected with Cryptococcus, DCs upregulate inducible NOS expression and recruit neutrophils and M1 macrophages to the lungs during infection." (PMID 33262956, 2020). "Infection of IL-10 KO mice increased the expression of YmI, FIZZ and Mannose Receptor (tissue healing markers) that remained unchanged upon treatment with fenofibrate." (PMID 33072115, 2020). "It was also shown that alveolar macrophages produce anti-inflammatory cytokines such as IL-10, especially during the resolution of the infection." (PMID 33133080, 2020). "Several studies have indicated that IL-10 protects the host during infection by limiting pathogen-induced immune pathologies, but other studies have shown that IL-10 can directly inhibit microbial killing by phagocytes, compromising host defense." (PMID 31819956, 2020). "Gene expression of IFNB1, TNF, and IL-10 was measured 24 h following infection with Mtb H37RV at MOI of one." (PMID 33240287, 2020). "It has been recently reported that IL-6 plays an important role in rendering protective immune response against SbRLD mediated infection by lowering IL-10 level." (PMID 33240825, 2020).
infection (continued). "The Il10 mRNA level was substantially decreased in BMDMs at 18 h but significantly increased at 6 h after Mabc infection." (PMID 32155958, 2020). "By contrast, cytokines, such as IL-10, deactivate infected cells and contribute to increasing infection." (PMID 32526867, 2020). "We extended the network of cytokines and chemokines by adding IL-10 as a major immune-suppressive cytokine responsible for achieving steady-state values after successfully fighting the infection." (PMID 33270742, 2020). "We observed down regulation of IL-22 and IL-10 in spleen of salmon at chalimus stage of infection and an increase in IL-1β, TNF-α and IL-8 at subsequent pre-adult stage in group 2." (PMID 33006991, 2020). "IL-10 levels were lowest in those with mild infection, which were significantly lower than in those who had mild illness, but prolonged shedding of the virus (p = 0.02)." (PMID 33199778, 2020). "Conversely, patients with moderate and severe endoscopic and histological activity with UC and HP-positive infection showed some increased levels of IL-10 compared with HP-negative infection (P < 0.05)." (PMID 32695157, 2020). "IL-10 has been shown to be critical in curbing mortality from infection, and its absence in knockout mice leads to increased susceptibility to inflammatory and autoimmune disorders." (PMID 32758231, 2020). "Here, our observation reveals that the BHU569 strain can produce more IL‐10 upon infection via ERK1/2 pathway by higher upregulation of phospho‐ERK1/2 level than the sensitive Ag83 strain." (PMID 32031337, 2020). "For the intravenous infection, mice infected with strain P15 had significantly higher production in the brain of the Th2 cytokines IL-4 and IL-10, as well as the inflammatory cytokine TNF-α." (PMID 33103620, 2020). "Other experimental infections of mouse MG with either S. aureus or E. coli showed an early contribution of IL-17 and Th17 cells to the control of infection, rapidly followed by IL-10 and probably regulatory T cells (Treg) intervention." (PMID 33059767, 2020). "In the case of systemic infections with Listeria monocytogenes and Y. pestis, approximately 50% of blood NK cells became IL-10+, and the cytokine was produced by a NK cell subset circulating in blood prior to the infection." (PMID 33101315, 2020). "When variants were grouped according to time post-infection, TF PSV induced the release of higher levels of IL-10 than their CI counterparts although this relationship varied across MDDC donors." (PMID 31978062, 2020). "B-cells seem to play a dual role in the immune system: antibody producing subtypes protect against infection, however, interleukin-10 (IL-10) producing subtypes supress immunity." (PMID 32392257, 2020). "The control of the infection was implemented by directly eliminating effector cells in an IL-10 and/or perforin-dependent manner." (PMID 32117218, 2020). "As the infection progresses, the immune response, modulated in part by IL-10, shifts to a mixed Th1/Th2 profile and then to a Th2 profile by 6 dpi with a significant increase of IL-4, IL-5 and IL-13 levels." (PMID 33023672, 2020). "Lower levels of the antiinflammatory cytokines, IL-10 and IL-13, after 2 wk of infection, followed by a significant increase in IL-10 levels after 3 wk of infection in CSE−/− mice reflects controlling mechanisms of the proinflammatory response in CSE−/− mice." (PMID 32139610, 2020). "On the other hand, plasma IL-10 was higher in animals fed a normolipidic diet when compared to the high-fat diet, and treatment with simvastatin, as well as infection, increased levels of this interleukin in animals treated with a high-fat diet." (PMID 32596277, 2020). "In L. infantum–infected RAW 264.7 cells, the presence of IL-10 in culture supernatants at 24 h post-infection was also reported." (PMID 32596164, 2020).